SMARCA2 (SWI/SNF related BAF chromatin remodeling complex subunit ATPase 2)
Diseases named in the same sentence as SMARCA2 in open-access papers (continued):
Sharing a sentence is not in itself a finding about the gene and the disease.
cancer (continued). "It has been shown to degrade SMARCA2 and SMARCA4 in various cancer cells, deplete SMARCA2 in SMARCA4-mutant AML, and cause decreased cell proliferation and cell death." (PMID 36770884, 2023). "SMARCA4 (BRG1) and SMARCA2 (BRM) are the two critical components of SWI/SNF ATPases that use ATP to generate energy for nucleosome remodeling, which is often mutated or silenced in cancer." (PMID 36844227, 2023). "Whereas ARID1A and SMARCA4 have more dominant roles in cancer, their closely paralogs, ARID1B and SMARCA2, frequently mutated in CSS and NCBRS, respectively." (PMID 36633435, 2023). "Eventually, seven ATPCR encoding genes, including ATRX, CHD5, CHD7, SMARCA4, SMARCA2, EP400, and ACTB, were identified as driver genes by at least two algorithms in certain cancer types." (PMID 35789070, 2022). "Our tool compound, ACBI2, shows selective degradation of SMARCA2 over SMARCA4 in ex vivo human whole blood assays and in vivo efficacy in SMARCA4-deficient cancer models." (PMID 36216795, 2022). "Although SMARCA2 has been found in a wide range of human cancers, the importance of the altered expression or dysfunction of the SMARCA2 protein in various cancers is not fully understood." (PMID 35289322, 2022). "Due to the concept that SMARCA4-mutant cancers are vulnerable to SMARCA2 inhibition, selectively degrading SMARCA2 has been an important therapeutic strategy." (PMID 36361605, 2022). "Most notably, functional genomic screens to identify gene dependencies have identified the paralog, SMARCA2, as a synthetic lethality in cancers with inactivated SMARCA411,12." (PMID 36357397, 2022). "It correlates with cancer aggressiveness and poor prognosis, suggesting a suppressive role of SMARCA2 in these tumors." (PMID 34315468, 2021). "In some cases, synthetic lethality is caused by the concomitant knockout of two mutually exclusive paralogues: Tumours with a SMARCA4 deficiency are sensitive to SMARCA2 depletion, and ARID1B is required for survival of ARID1A-mutant cancers." (PMID 33941852, 2021). "Reactivation of SMARCA2 by a histone deacetylase inhibitor rescues IP3R3 expression and enhances cisplatin response in SMARCA4/2-deficient cancer cells both in vitro and in vivo." (PMID 34518526, 2021). "TCF21 and SMARCA2 have been reported to participate in the multiple steps of the invasion of several cancers, such as proliferation, chemoresistance, and migration, suggesting the convergence of targets among the different cancers." (PMID 33968720, 2021). "A number of gene nodes linked to drug resistance in other cancer types (including CAT, TRIM59, ANXA2, ADM, AJUBA, HSPA1A/1B, LAMC2, TRIM14, KRT8, KRT18, KRT9, CLDN1, and SMARCA2) were also down-regulated in PARPis-sensitive AsPCs." (PMID 33213473, 2020). "The loss of chromosome 9p, the SMARCA2 gene location, results in BRM loss and enhanced cancer aggressiveness." (PMID 31722744, 2019). "Our data suggest that SMARCA4 inhibition would allow for a selective, cancer-cell directed therapy sparing normal, SMARCA2-expressing cells and tissues." (PMID 31406271, 2019). "Similar to the ARID1A/ARID1B functional dependency, SMARCA4 mutant cancer cells showed sensitivity to SMARCA2 depletion." (PMID 31769422, 2019). "SMARCA4/BRG1 and SMARCA2/BRM, the two mutually exclusive catalytic subunits of the BAF complex, display a well-established synthetic lethal relationship in SMARCA4-deficient cancers." (PMID 31406271, 2019). "Here, we performed a computational meta-analysis using gene expression, prognosis, and clinicopathological data to clarify the role of SMARCA4 and the alternative SWI/SNF ATPase SMARCA2 (BRM) in cancer." (PMID 29391527, 2018). "In order to clarify this complex scenario, we have now used data from The Cancer Genome Atlas (TCGA) and other databases to investigate the levels of SMARCA4 and SMARCA2 mRNAs in several types of cancer." (PMID 29391527, 2018).
cancer (continued). "While a high expression of SMARCA4 is associated with aggressive tumors, a high expression of SMARCA2 is associated with benign differentiated tumors, suggesting that SMARCA4 and SMARCA2 play opposite roles in cancer." (PMID 29391527, 2018). "Although SMARCA4 and SMARCA2 display high homology and presumably have overlapping functions, other observations suggest that they have different roles in cancer." (PMID 25391308, 2014). "Its diversity in function has been recently demonstrated by contrasting sets of publications about the role of one of its two catalytic subunits, Brahma (BRM, or SMARCA2), in cancer." (PMID 25774356, 2014). "Exciting new evidence is emerging from the discovery that ARID1A-mutant cancer cells are highly vulnerable to loss of ARID1B expression, and similarly for BRG1/SMARCA4-mutated cancers to the loss of BRM/SMARCA2." (PMID 25927994, 2014). "Thus, simultaneous suppression of CREBBP and EP300, but not that of either alone, causes synthetic lethality in SMARCA4/SMARCA2-deficient and SS18–SSX fusion cancers." (PMID 39625239, 2025). "Combining epigenetic drugs with previously identified therapeutic vulnerabilities of BRG1-LOF cancers (such as SMARCA2-degraders or inhibitors of Aurora kinase, CDK4/6, oxidative phosphorylation, or others) will likely yield greater responses and warrants further investigation." (PMID 41008934, 2025). "To further confirm that KREMEN2 is a determinant of synthetic lethality through simultaneous inhibition of CBP/p300 in SMARCA4/SMARCA2-deficient cells and SS18–SSX fusion cancer cells, we investigated whether depleting KREMEN2 affects cell viability." (PMID 39625239, 2025). "Furthermore, treatment with CBP/p300 dual inhibitor suppressed the growth of xenografts derived from SMARCA4/SMARCA2-deficient and SS18–SSX fusion cancer cells, resulting from repression of KREMEN2 and induction of apoptosis." (PMID 39625239, 2025). "The most common example of these interactions is provided by the combination of mutually exclusive gene paralogues, such as in cancers with ARID1A mutation that require ARID1B for survival or tumors with BRG1 deficiency, which are sensitive to SMARCA2 depletion." (PMID 41278204, 2025). "Thus, SMARCA4/SMARCA2-deficient and SS18–SSX fusion cancer cells depend on the expression of KREMEN2." (PMID 39625239, 2025). "SMARCA4 and SMARCA2 are two important genes in the field of cancer genetics." (PMID 38656564, 2024). "Additionally, low SMARCA4 expression positively correlates with SMARCA2 CRISPR knockout effects when considering all cancer cell lines." (PMID 39174852, 2024). "We have recently reported a consistent negative association of SMARCA2 expression with cancer de-differentiation status." (PMID 36674511, 2023). "Given that either loss-of-function point mutations or inactivation of SMARCA4 have been outlined in several hematological malignancies, targeting its paralog (SMARCA2) might be a potential therapeutic alternative for the treatment of these cancers." (PMID 36810086, 2023). "Therefore, the use of selective inhibitors in inhibiting SMARCA2 activity has become a new therapeutic strategy in SMARCA4-mutant cancers." (PMID 36770884, 2023). "A pan-cancer study showed an opposing prognosis for SMARCA2 and SMARCA4 in several types of tumors." (PMID 36464671, 2022). "The role of BRM-driven AS in cancer is further complicated by the fact that the SMARCA2 gene may be transcribed to 9 mRNA isoforms, which give rise to five different proteins." (PMID 35158828, 2022). "Thus, there is therapeutic potential in targeting the functional domains of SMARCA2 and SMARCA4 in some cancer contexts, particularly when there is a deficiency in one ATPase." (PMID 35323214, 2022).
cancer (continued). "Using clinicopathologic data, we demonstrated that higher‐grade tumors display significant upregulation of ATAD2 and SMARCA4 expression, and downregulation of SMARCA2 expression, which further confirms a universal relation of these BrD proteins' expression with cancer stemness." (PMID 35049055, 2022). "The lack of efficacy of SMARCA2/4 BRD inhibitors in SMARCA4-mutated cancers suggested the ATPase domain rather than the BRD as the therapeutically relevant target in oncology, which was confirmed by genetic complementation studies." (PMID 33941852, 2021). "Furthermore, we observed a significant positive correlation between ITPR3 and SMARCA2 in these ovarian (n = 11, r = 0.825) and lung (n = 48, r = 0.584) cancer cell lines with low SMARCA4 expression." (PMID 34518526, 2021). "Our study provided proof-of-principle data supporting that HDACi may be a potential therapeutic strategy to stimulate ITPR3 transcription through SMARCA2 reactivation and sensitize SMARCA4/2-deficient cancers to chemotherapy." (PMID 34518526, 2021). "In contrast to other cancer types where experimental SMARCA2 inhibition is synthetic lethal with SMARCA4 loss, SMARCA2 silencing may cooperate with SMARCA4 loss in SMARCA4/2-deficient SCCOHT and NSCLC for cancer development." (PMID 34518526, 2021). "In addition to pan-cancer analysis, SynLeGG offers investigation of tissue-specific GDRs and recovers established relationships, including synthetic lethality for SMARCA2 with SMARCA4." (PMID 33997893, 2021). "Cancers with SMARCA4 deficiency, a genetic alteration frequently observed in malignant solid tumours or lung adenocarcinomas, for example, show a dependency on the paralogue SMARCA2." (PMID 33941852, 2021). "However, other subunits such as SMARCE1 (BAF57), SMARCA2 (BRM) and SMARCAD1 (BAF60a) were implicated to promote cancers." (PMID 33670012, 2021). "By applying SMARCA2 reconstitution and knock-out strategies in ESCC cell models, we define a novel synthetic lethal relationship reciprocal to the SMARCA2 dependency observed in SMARCA4-deficient cancer cells." (PMID 31406271, 2019). "However, other recent reports point to essential roles of SMARCA4 and/or SMARCA2 in cell survival and proliferation in some types of cancers, complicating our understanding of the role of these ATPases in cancer." (PMID 29391527, 2018). "Though mutations in SMARCA2 are reported in a rare developmental disorder, the gene has not yet been directly related to any specific cancer." (PMID 26359351, 2015). "Therefore, this study examined the potential for expansion and adaptation of simultaneous CBP/p300 inhibitors for use against cancers with SS18–SSX fusion and the majority of SMARCA4/SMARCA2-deficient in addition to SMARCB1 deficient, which was reported previously." (PMID 39625239, 2025). "Although SMARCA2 degraders would have the potential to be developed as single agents in the clinic to treat SMARCA4mut cancers, we have begun to address whether rational and ubiquitously active pharmacologic combinations exist for SMARCA2 degraders in SMARCA4mut cancers." (PMID 36357397, 2022). "We aimed to achieve orally bioavailable molecules that selectively degrade the BAF Chromatin Remodelling complex ATPase SMARCA2 over its closely related paralogue SMARCA4, to allow in vivo evaluation of the synthetic lethality concept of SMARCA2 dependency in SMARCA4-deficient cancers." (PMID 36216795, 2022). "Similarly SMARCA4-mutant cancers are vulnerable to SMARCA2 inhibition." (PMID 36361605, 2022). "Thus, the opposing functionalities of the closely related BRD7 and BRD9 proteins, as well as in SMARCA2/4, highlights the importance of understanding the roles of specific bromodomain-containing proteins in cancer biology in order to effectively develop new therapeutic strategies." (PMID 34298819, 2021). "Constituent genes (e.g., SMARCB1, SMARCA4, SMARCA2, and SS18) of the SWI/SNF complex often harbor genetic abnormalities in various cancers." (PMID 39625239, 2025).
cancer (continued). "For example, SMARCA2 is a nuclear subunit of the SWI/SNF complex, whose ATPase, helicase, scaffolding and bromodomain functions are important in cancer." (PMID 40266852, 2025). "The increased sensitivity of BRG1-LOF tumors to degraders or inhibitors of SMARCA2, aurora kinase, CDK4/6, oxidative phosphorylation, and other survival factors demonstrates the broad therapeutic vulnerabilities of these cancers." (PMID 41008934, 2025). "For example, the chromatin remodelling enzymes SMARCA2 and SMARCA4 are required for the proliferative capacity of numerous cancer cell lines." (PMID 41416925, 2025). "A wide variety of benign and malignant tumors with alterations in several genes belonging to the SWI/SNF complex have been described, including SMARCB1, SMARCA4, SMARCA2, and ARID1A." (PMID 39590317, 2024). "ACBI1 effectively induced the swift, specific, and total degradation of SMARCA2, SMARCA4, and PBRM1 targets within MV-4-11 cancer cells." (PMID 38389844, 2024). "Researches indicated that insufficient SMARCA2 and/or SMARCA4, the ATPase activity subunits of SWI/SNF complexes, sensitized the cancer cells to chemotherapy or radiotherapy." (PMID 39627201, 2024). "Due to the mutual exclusivity of SMARCA4 and SMARCA2 as catalytic subunits of the SWI/SNF complex, a common approach to targeted treatment of SMARCA4-mutant cancers is synthetic lethality." (PMID 37433987, 2023). "SMARCA2 and SMARCA4 exhibit a synthetic lethal relationship in cancer that can be exploited therapeutically." (PMID 35323214, 2022). "A recent study by Farnaby developed an optimized chemical ACBI1 that cooperatively targets SMARCA2, SMARCA4, and PBRM1, exhibiting significant antiproliferative and cell death-inducing effects in SMARCA4-mutant cancer cells." (PMID 36361605, 2022). "ACBI1 induced selective, fast and complete degradation of the engaged targets SMARCA2, SMARCA4 and PBRM1 in MV-4-11 cancer cells with DC50 of 6 nM and 11 nM for SMARCA2/4, respectively." (PMID 35983982, 2022). "While bromodomain inhibition was not as effective as ATPase inhibition at curbing growth of some SWI/SNF mutant cancers, PFI-3, a small molecule selective for the SMARCA4/SMARCA2/PBRM1 bromodomains, sensitized cancer cells to DNA-damaging agents." (PMID 35323214, 2022). "A number of bromodomain genes are consistently decreased in the TCGA cancer dataset, including KAT2B, SMARCA2, zinc finger MYND domain-containing protein 11 (ZYMND11), and mixed-lineage leukemia (MLL)." (PMID 34298819, 2021). "In BC, the low expression of SMARCA2 correlates with higher PRKAA1 and PKM2 expression indicative of its important role in the control of metabolic processes in this cancer type." (PMID 32073734, 2020). "These examples depict a striking exemption of the concept of hard-wired SMARCA2/SMARCA4 paralog dependency and constitute a potential mechanism for resistance to BAF targeted cancer therapies." (PMID 31406271, 2019). "Strikingly, all of the chromatin remodeling factors (SMARCA1, SMARCA2, SMARCA4 and SMARCA5) are shown to be differentially expressed in diverse cancer cell types." (PMID 26030138, 2015). "Unfortunately, those inhibitors, despite their ability to penetrate cells and potently block SMARCA2 bromodomains, did not exert antiproliferative effects in cancer cells." (PMID 40181550, 2026). "Notably, this mechanism is conserved in human salivary gland tissue and can be induced using SMARCA2-targeting PROTAC degrader, a therapeutic class under active development for cancer treatment." (PMID 41756468, 2026). "In contrast, analysis of the depmap datasets revealed lower SMARCA2 mRNA levels in NB cell lines compared to other cancer cell lines, and SMARCA2 was not identified as essential to NB cell growth." (PMID 39174852, 2024).
cancer (continued). "We report AU-15330 as a novel, highly specific and VHL-dependent PROTAC degrader of SWI/SNF ATPase components (SMARCA2, SMARCA4 and PBRM1) that shows preferential cytotoxicity in enhancer-binding transcription factor-addicted cancers at low nanomolar concentrations." (PMID 34937944, 2022). "An integrative analysis identified that enrichment of F. nucleatum was associated with host gene promoter methylation, including hypermethylation of tumor suppressor genes LXN and SMARCA2, for which gene expressions were downregulated in the HNSCC cohort from The Cancer Genome Atlas." (PMID 33218162, 2020). "Nonetheless, in some cancers with lack/low BRM level, no mutations and no hypermethylation were found in the SMARCA2 locus suggesting the existence of other mechanisms involved in the control of BRM expression or protein stability." (PMID 31722744, 2019). "Further in vitro studies demonstrated that targeting the ATPase activity of SMARCA2 and SMARCA4 might be a more potent target in cancer." (PMID 31769422, 2019). "In the majority of cancers lacking BRM, no mutations of the SMARCA2 gene were found suggesting that epigenetic regulation plays more crucial role in the BRM inactivation." (PMID 31722744, 2019). "The lack of SMARCA2 expression in cancer cells might therefore be related to cell-specific and epigenetic regulation mechanisms." (PMID 31406271, 2019). "However, the molecular studies demonstrating the precise role of SMARCA2 in the regulation of cancer stemness across distinct types of solid tumors are insufficient to make an unequivocal decision on whether SMARCA2 is a negative cancer stemness regulator." (PMID 36674511, 2023). "Moreover, SMARCA2-negative expression was significantly associated with SOX-2-negative expression, whose presence maintains the stem cell phenotypic characteristics of cancer cells." (PMID 35289322, 2022). "Reciprocal to the known dependency of SMARCA4-deficient cancer cell lines on SMARCA225–27, the majority of SMARCA4-dependent ESCC cell lines (KYSE-270, KYSE-30, KSYE-510 and COLO-680N) displayed low or non-detectable levels of SMARCA2 mRNA and protein expression." (PMID 31406271, 2019). "In these regards, SMARCA2 (also known as BRM), another catalytic subunit of the SWI/SNF complex, has been reported to form a double-negative feedback loop with miR-199a-5p in cancers." (PMID 36902184, 2023). "This concept is further extended to non-ESCC cancer cell models, indicating SMARCA4 as a potential therapeutic target in tumors with low or absent expression of SMARCA2." (PMID 31406271, 2019). "The first study considering direct BRM targeting was development of selective SMARCA2/4 bromodomain inhibitor (PFI-3), although PFI-3 did not reveal antiproliferative effect in cancer cells." (PMID 31722744, 2019). "In this case, cancer cells lacking SMARCA4 or ARID1A, two core components of the SWI/SNF complex, become dependent on the corresponding paralogs, SMARCA2 and ARID1B, respectively." (PMID 28430577, 2017). "However, restoration of SMARCA4 or SMARCA2 in SMARCA4/2-deficient cells did not consistently suppress SLC38A2 expression, suggesting that the elevated SLC38A2 levels in SMARCA4/2-deficient cancer cells may be an adaptation to suppressed glycolysis rather than a direct transcriptional regulation." (PMID 37210563, 2023).